AR (androgen receptor)
Diseases named in the same sentence as AR in open-access papers (continued):
Sharing a sentence is not in itself a finding about the gene and the disease.
tumor (continued). "Thus, while AR was found to be expressed in virtually all luminal cells, half of the basal cells, and 60% of fibroblasts in the normal prostate, there was a loss of AR particularly in the fibroblasts and the tumor cells during the evolution of cancer." (PMID 38660133, 2024). "Therapy: Given the strong associations of AR signaling with impaired anti-tumor immunity via T-cell exhaustion detailed above, combining anti-androgen therapies with immune checkpoint inhibitors may augment responses to systemic immunotherapies." (PMID 38398136, 2024). "High AR/ER and residual tumor Ki67 were associated with poor DFS in the NAC group." (PMID 37345052, 2023). "LCMT1 loss activates AR signaling and promotes castration-independent tumor growth." (PMID 37644036, 2023). "Numerous studies have identified mechanisms of castration resistance, including tumor cell‐intrinsic ones, such as androgen receptor (AR) amplifications and mutations, as well as microenvironmental ones, such as the enrichment of immunosuppressive myeloid‐derived suppressor cells (MDSCs)." (PMID 37070472, 2023). "This inter-patient diversity is of relevance to efforts of investigating AR-associated breakpoints as biomarkers for tracking tumor clones and treatment selection that will require patient-specific probes or broad approaches to sequence chromosome X at sufficient depth." (PMID 37563129, 2023). "In castration-resistant prostate cancer (CRPC) cells, VER-155008 suppressed the expression of full-length androgen receptor (AR) and AR splice variant 7 (ARv7) through Y-box binding protein 1 (YB-1) inhibition, which makes it an attractive anti-tumor agent for treating CRPC." (PMID 37189349, 2023). "In addition, the two inhibitors also cause down-regulation of AR protein expression, which papers attribute to their anti-tumor efficacy." (PMID 36674820, 2023). "Secondly, testosterone-induced rearrangements of AR may cause downregulation in PSMA expression while the tumor maintains its viability." (PMID 37509723, 2023). "In addition to initiating tumour growth, there is also evidence that AR signalling is associated with DNA damage and changes in autophagy." (PMID 36674785, 2023). "A great number of AR antagonists initially had been found effective in tumour remission; however, most PCa relapsed that caused by pre-translational resistance such as AR mutations to turn antagonist into agonist, and AR variants to bypass the androgen binding." (PMID 36203075, 2023). "In 5–10% of CRPC cases, AR gene rearrangements exist as the only AR alteration detectable, and in this context they promote synthesis of tumor-unique AR variants (AR-V) that lack the AR ligand binding domain and possess constitutive activity that supports growth of CRPC cells." (PMID 37636316, 2023). "Similarly, HCC tissues exhibit elevated expression of HOXB13 and AR compared to normal tissues, implying their tumour‐associated properties and clinical relevance." (PMID 38093528, 2023). "AR protein analysis of primary tumor samples and tumor-derived cell lines verified AR expression but also found that 30% of AR-expressing tumors and cells also expressed AR-V7, where the variant is always co-expressed with FL-AR." (PMID 37626712, 2023). "Additional hypothesized mechanisms include AR gene amplification, AR gene mutations, ligand-independent activation of the AR, involvement of coregulators, and recruitment of tumor stem cells." (PMID 36900412, 2023). "The loss of TOMM20 in PCa tumor specimens might become a useful predictor of PCa sensitivity to AR antagonists." (PMID 37563661, 2023). "Besides their role in CRPC, AR variants lead to the expression of genes involved in tumor progression." (PMID 34919781, 2022). "The upfront use of ARPI enhancing the pressure of ADT on the AR pathway or causing a significant reduction in circulating and tumour levels of testosterone would avoid the onset of these resistance mechanisms, thus delaying the beginning of the castration resistance phase." (PMID 36547161, 2022).
tumor (continued). "However, although some genes in the hallmark AR response gene set were upregulated in both R and NR tumors, there was also a subset of these genes specifically increased in R tumor only and a subset increased in NR tumors only." (PMID 35603787, 2022). "Thus, as occurs in some human cancers, including PC, AR cytoplasmic expression can be associated with different signaling pathways, leading to aggressive tumor behavior." (PMID 35163087, 2022). "As cell plasticity is closely linked to tumor progression, it may be interested to pay attention to long‐term consequences of AR targeting on PCa cell feature." (PMID 34919781, 2022). "However, acquisition of resistance mechanisms that restore androgen supply or AR activity in the tumor such as AR amplifications, mutations or splice variants eventually can result in castration resistant prostate cancer (CRPC)." (PMID 35109899, 2022). "Moreover, low stromal AR expression is linked to tumor resistance to ADT and relapse in PCa patients." (PMID 36551674, 2022). "Our hypothesis was that AR splice variants exert their tumor-promoting activity by modulating the intrinsic DNA repair machinery." (PMID 36139600, 2022). "Such AR expression is generally associated with older patient age, lower KI-67, non-ductal histology (includes all other histologic subtypes including lobular, medullary, metaplastic, and apocrine), grading G1–2, and lower tumor-infiltrating lymphocyte levels." (PMID 37435469, 2022). "Besides, constitutively active AR variants would pathologically upregulate EMT genes to promote tumor progression." (PMID 34919781, 2022). "However, due to mutations and the continuous expression of AR during tumor progression, hormone therapy often fails." (PMID 35055079, 2022). "Higher levels of AR contribute to tumor cell proliferation, and hypoxia conditions inhibit its transcription, thus causing a decrease in its expression in the tumor core, and this limits tumor cell proliferation in the tumor core." (PMID 36361793, 2022). "Our data suggests that hypoxia-induced promotion of AR expression and activation may underpin a target-associated resistance to AR-directed therapy intrinsic to tumor cells." (PMID 35302608, 2022). "Assessments of AR-V7 mRNA in circulating tumor cells (CTC) showed that the presence of AR-V7 mRNA in CTCs was associated with increased resistance to AR-targeting therapies and that AR-V7 mRNA may be a treatment selection marker in patients with CRPC." (PMID 36212458, 2022). "To test whether the UGT2B28-associated tumor growth was reliant on AR signaling, we subcutaneously injected VCaP NT, UGT2B28 KD, and UGT2B28 R cells in castrated mice." (PMID 35954173, 2022). "Therefore, our data of identifying reduced atypical Myc+ basal cells in PIN tissues of HiMyc-ARKO mice implicate an underlying mechanism by which stromal AR deletion in Gli1-lineage cells impairs prostatic oncogenesis and tumor development." (PMID 36323713, 2022). "In addition to the pre-existing heterogeneity of the tumor, the application of second-generation AR antagonists is associated with treatment-induced heterogenetic evolution." (PMID 35864113, 2022). "In addition, AR was regarded as a protective factor in RCC because the expression of AR was associated with lower tumour stage, unclear grade and prognosis." (PMID 35452181, 2022). "Moreover, the luminal BC HER2+ AR+ was associated with lower histological grade (G2) and lower tumor size, higher PR expression, and a lower HER2 intensity of expression (2+)." (PMID 35052843, 2022). "On the basis of these results, we hypothesized that preexisting differences in AR cistrome and AR-regulated transcriptome in CRPC tumors play an important role in SPT-mediated tumor inhibition and predispose tumor cells to inhibition by SPT." (PMID 35603787, 2022). "Moreover, gain-of-function and point mutations in AR results in increased activation and decreased specificity, respectively, both resulting in tumor cell survival." (PMID 35686097, 2022).
tumor (continued). "The diverse response phenotypes associated with SPT tumor inhibition highlighted the need for a signature, and we proposed that the differences in AR signaling in the parental pretreatment tumors are highly clinically relevant to outcomes of the SPT treatments." (PMID 35603787, 2022). "AR activates the transcription of a variety of proteins and is closely associated with cell proliferation and apoptosis following binding to its ligand, thus fueling tumor progression." (PMID 35370971, 2022). "Additionally, not only the ERβ but also the AR were negatively associated with the tumor content of SO4E1 (p = 0.007 and p = 0.042, respectively)." (PMID 36006309, 2022). "Hence, a detailed understanding of PCa biology and elucidation of the mechanisms underlying AR-driven tumor aggressiveness will help develop novel treatments for patients with advanced PCa." (PMID 36127329, 2022). "Tumor inhibition is associated with altered fatty acid metabolism and reduced AR signaling." (PMID 36358940, 2022). "However, positive AR expression was demonstrated to be significantly associated with male patients, lower pathological grade and earlier tumour stage of RCC." (PMID 35452181, 2022). "Therefore, it appears that CHD1 acts as a tumor suppressor by preserving the integrity of the AR cistrome, whereas its loss leads to the reprogramming of the AR cistrome and an altered AR-associated transcriptome." (PMID 36212399, 2022). "A number of studies showed that AR expression was significantly increased in type I EC and was associated with favorable prognostic factors such as early stage of cancer, low grade, lymph node negativity, and reduced tumor recurrence rate." (PMID 36358974, 2022). "However, the fundamental mechanisms underlying the AR functioning as a tumor promoter in inducing prostatic oncogenesis still remain elusive." (PMID 35902588, 2022). "Among the various factors elsewhere excellently discussed, PC progression is often characterized by abnormal AR-mediated signaling activation or AR variants, which might help the tumor to achieve ADT unresponsiveness." (PMID 35222290, 2022). "However, our results first identified AR as a risk factor for Xp11.2 tRCC and provided a novel molecular mechanism for the age‐dependent prognostic difference in tumour progression." (PMID 35452181, 2022). "Thus, tumor evolution seems to be associated with an adaptive response of AR signaling bypassing ADT and antagonist activity and perhaps selecting for a more aggressive drug resistant CRPC." (PMID 33810413, 2021). "This in turn will reduce downstream AR oncogenic activity eventually causing tumour to regression." (PMID 33993099, 2021). "As discussed in the previous sections, following activation, both NF-κB and AR translocate into the nucleus and bind to their respective DNA response elements, leading to the expression of many genes associated with aggressive tumor growth and endocrine resistance." (PMID 35582006, 2021). "However, studies also showed that androgen had the capacity to promote M2 macrophage polarization, supporting the tumor-promoting role of AR signaling in PCa-associated macrophages." (PMID 34692685, 2021). "In particular, we hypothesize that SNAI2 deficiency in pretreatment tumor cells render them susceptible to cell death induced by AR signaling inhibition." (PMID 34322653, 2021). "Most of the known mechanisms are based on the reactivation AR pathway despite a low level of blood testosterone, including AR gene mutation, emergence of AR splice variants, amplification and overexpression of the AR protein or intraprostatic production of androgens by tumor cells themselves." (PMID 34359692, 2021).
tumor (continued). "miR-1246 in tumor EVs caused IL-6 induction through AR downregulation in ECs." (PMID 34226586, 2021). "However, based on our analysis, it is possible that the tumor suppressor action of miR-613 is associated with AR loss, considering that it was found with higher expression in QNBC when compared to TNBC samples." (PMID 34768979, 2021). "Tumours with the T878A and F877L AR mutations are shown to be sensitive to Darolutamide treatment and therefore Darolutamide may be a potential treatment option against such resistance mechanism." (PMID 33993099, 2021). "Given the critical role of AR in PCa, we speculated that these somatic mutations could potentially alter the transcriptional activity of the tumor and potentially impact PCa growth and proliferation." (PMID 33975627, 2021). "In contrast, higher levels of testosterone associated with lower levels of AR/ER ratio in >50 years tumor group may indicate their preferential conversion to estradiol leading to more ER driven tumors in the post-menopausal age group." (PMID 34234742, 2021). "Androgen receptor seemingly acts as a tumor-suppressing factor in PCa-associated macrophages." (PMID 34692685, 2021). "However, previous studies have reported associations between AR protein expression by IHC with smaller tumor size and lower proliferative index (Ki-67 level)." (PMID 34571711, 2021). "Finally, combining these results with whole genome sequencing of primary and metastatic PCa, we identified and characterized a non-coding somatic mutation that significantly impacted AR enhancer activity of a critical tumor suppressor." (PMID 33975627, 2021). "Interestingly, ERG-positive, and PTEN-loss tumours were associated with reduced AR expression, suggesting androgen-independent survival mechanisms in these tumours." (PMID 35008330, 2021). "AR is the classical target for PCa prevention and treatment, but more recently estrogens and their receptors have also been implicated in both development and tumor progression." (PMID 33451122, 2021). "To evaluate whether reduced tumour growth was linked to inhibition of AR transactivation, we also determined the levels of nuclear AR in tumour sections from treated and untreated mice." (PMID 34417456, 2021). "However, CRPC tumor cells through AR point mutations, AR amplification, changes of androgen biosynthesis, and other mechanisms make CRPC resistant to drugs such as enzalutamide." (PMID 34545063, 2021). "Rucaparib was also approved by the FDA for patients with deleterious BRCA1 or BRCA2 mutation (germline and/or somatic)‐associated mCRPC who have been treated with androgen receptor‐directed therapy and a taxane‐based chemotherapy based on the tumour testing findings of the TRITON2 study." (PMID 33630412, 2021). "Thus, it is possible that other factors in the tumor microenvironment contribute to the regulation of αVβ3 integrin and αVβ6 integrin expression after AR signaling loss." (PMID 33481853, 2021). "Moreover, activation of the androgen receptor by IL-6 in some subtypes of PC is associated with increased growth of tumor cells in vitro and in vivo." (PMID 34868907, 2021). "Second, miR-1246 in tumor EVs caused IL-6 induction through AR downregulation in ECs." (PMID 34226586, 2021). "These cells are naturally unresponsive to the blockade of androgen signaling and would provide a reservoir of resistant cells which produce tumor-regenerating cells either by the acquisition of inactivating mutations or at the cessation of the AR inhibitory treatment." (PMID 33477370, 2021). "SSTR1 was linked to androgen receptor (AR) expression and tumor metastasis." (PMID 33995646, 2021). "Recent studies have suggested that EVs from tumor cells may transport AR and its variants to recipient cells." (PMID 34359692, 2021).
tumor (continued). "Similarly, expression of AR-V7 (assessed as AR-V7 mRNA and protein levels from tissue biopsies, circulating tumor cells [CTCs], and whole blood) is associated with resistance to AR-targeted therapies." (PMID 34638258, 2021). "More aspects linked to the IL1 pathway have so far been described in UCB, such as IL1B-induced cisplatin-resistance by up-regulation of Aldo-keto reductase 1C1, IL1 dependent intra-tumoral androgen receptor (AR) signaling, T-cell attraction, and recruitment of tumor-associated fibroblasts." (PMID 34070905, 2021). "In terms of survival, population- based studies support the hypothesis that there is an inverse association between tumor AR expression and mortality in women with ER positive BC." (PMID 33802610, 2021). "Interestingly, one of the affected enhancers was found to interact with the TSS of ZBTB16, a well-known AR-regulated tumor suppressor that is commonly mutated in CRPC." (PMID 33975627, 2021). "Primary and acquired resistance to AR-targeted therapies has been associated with mutations or amplification of AR gene and the expression of AR splice variants (i.e., AR-V7) in circulating tumor cells (CTC) or in metastatic tissues." (PMID 33072600, 2020). "One of the mechanisms underlying this change is an enhanced AR expression in the tumor cell." (PMID 32085497, 2020). "Several aspects have so far been described, such as IL-1β induced cisplatin-resistance by up-regulation of Aldo-keto reductase 1C1, IL-1 dependent intra-tumoural androgen receptor signalling, T-cell attraction or stimulation and recruitment of tumour-associated fibroblasts." (PMID 33267794, 2020). "In addition, E2F1 is closely associated with AR function, both as an oncogene and a tumor suppressor." (PMID 32354165, 2020). "AR expression correlated with favorable clinicopathological features and lower proliferation index (Ki67), whereas loss of AR positively correlated with higher tumor grade, higher FIGO stage, and deep myometrial invasion." (PMID 33352741, 2020). "Notably, silencing of two lncRNAs (CRPC-Lnc #6: PRKAG2-AS1 and #9: HOXC-AS1) alleviated CRPC tumor growth, showing repression of AR and AR variant expression." (PMID 32704143, 2020). "Also, 22 variants in five genes [ICOSLG, NCOR1, KMT2C, HLA-A and AR] were found to be pathogenic/ likely pathogenic in other tumor types." (PMID 33075099, 2020). "However despite these limitations, the finding that AR positivity was associated with a better prognosis in ER positive tumours, especially in postmenopausal women is in keeping with other studies." (PMID 32928183, 2020). "Their incidence may increase during treatment with abiraterone and enzalutamide because, when AR signalling is more effective suppressed, clonal selection of tumour cells can enhance AR somatic mutations and the consequent aberrant transcription." (PMID 35582226, 2020). "Loss of tumor suppressor genes may enable these tumor cells to reexpress developmental TFs and to exhibit cell plasticity under selective pressure of potent AR inhibition (prostate) or EGFR inhibition (NSCLC)." (PMID 33297508, 2020). "It is likely to be mediated by the tumor suppressor effect of PR and is associated with a decrease in the Brn-3α expression, the primary modulator of the AR, ER transcriptional activity." (PMID 32102520, 2020). "The molecular mechanisms of loss of AR actions contributing to advanced tumor behavior remain unclear." (PMID 32365531, 2020). "Additionally, in the same study carried out in mice, ChIP analysis was performed with tumor associated DCs, as well as splenic DCs revealing ERα and AR expression by DCs from both tissues." (PMID 32714315, 2020). "In this tumor, additional mutations were identified in AR (A159T) and SDHA (T36I)." (PMID 32099073, 2020).